HIF1A (hypoxia inducible factor 1 subunit alpha)
Diseases named in the same sentence as HIF1A in open-access papers (continued):
Sharing a sentence is not in itself a finding about the gene and the disease.
Hypertension (continued). "Our findings demonstrate the significance of the HIF-1α/Hippo-YAP pathway in CIH-induced hypertension and vascular remodeling." (PMID 39732653, 2024). "PPI network analysis revealed three potential key targets—MMP9, HIF1A, and BCL2—that are significantly implicated in the treatment of hypertension with catechins." (PMID 39272451, 2024). "In conclusion, this study is the first to demonstrate that HIF-1α knockdown alleviates hypertension, inflammation, oxidative stress, and vascular remodeling in a CIH-induced hypertension model." (PMID 39732653, 2024). "HIF-1α silencing reduced hypertension, oxidative stress, inflammation, and the severity of vascular remodeling." (PMID 39732653, 2024). "2K1C-induced hypertension per se resulted in modest HIF-1α stabilization in tubular epithelial cells of the right kidney." (PMID 37435301, 2023). "HIF-1α expression has been studied in different models of experimental hypertension, and reported results are very variable." (PMID 37435301, 2023). "The number of HIF-1α-positive tubular epithelial cells in the medulla as well as in the cortex of the right kidney (exposed to systemic hypertension) was significantly increased after ICA treatment compared to placebo-treated 2K1C rats." (PMID 37435301, 2023). "Adding to the importance of this transcription factor, if HIF1A is overexpressed in pregnant mice, they develop hypertension and kidney dysfunction." (PMID 37759628, 2023). "The study involving a clinical specimen can further illuminate the role of miR-199a-5p in relieving OSAS with hypertension by targeting HIF-1α." (PMID 35935584, 2022). "In this study, we investigated the role of miR-199a-5p and HIF-1α in OSAS with hypertension by performing in vitro cell experiments and in vivo animal experiments." (PMID 35935584, 2022). "Luo and colleagues demonstrated that Ang‐II induced endothelial HIF‐1α gene expression via nuclear factor‐κB‐dependent pathway, which contributes to glomerular injury and promotes hypertensive chronic kidney disease." (PMID 35441828, 2022). "In this study, we investigated the role of miR-199a-5p and HIF-1α in OSAS-related hypertension by performing in vitro cell experiments and in vivo animal experiments." (PMID 35935584, 2022). "By establishing an animal model, we found decreased miR-199a-5p expression and increased HIF-1α expression in OSAS with hypertension." (PMID 35935584, 2022). "HIF1α is the major circulating bioactive factor in PE, and downregulated HIF1α can ameliorate the symptoms including hypertension and proteinuria in PE animal models." (PMID 33928137, 2021). "A related study showed that long-term over-expression of HIF-1α was a pathogenic factor leading to chronic kidney injury and stimulating the expression of HIF-1α in cells induced renal injury, hypertension and disease progression." (PMID 34168560, 2021). "In summary, FG-4592 treatment remarkably ameliorated hypertension and organ injury, possibly through stabilizing HIF1α and subsequently targeting eNOS, AGTR1, AGTR2, and oxidative stress." (PMID 34403364, 2021). "QYYY played an important role in the treatment of hypertensive renal damage by regulating metabolic reprogramming mediated by HIF-1α/PKM2 positive feedback loop and HIF-1α is a key target in the treatment of renal damage of hypertension by QYYY." (PMID 34168560, 2021). "On the other hand, persistent activation of HIF-1α promotes cardiac hypertrophy in hypertension and increased HIF-1α suppresses mitochondrial function." (PMID 34912235, 2021). "Conversely, HIF-1α and/or specific downstream targeted genes induce the development and perpetuation of hypertension." (PMID 34447792, 2021). "This contrasts with systemic hypertension where CIH induces overexpression of HIF-1α while inhibiting HIF-2α expression, making the elevation of both HIFs specific to PAH." (PMID 34447792, 2021).
Hypertension (continued). "Our experimental data demonstrated that QYYY improved renal injury of hypertension by regulating metabolic reprogramming mediated by HIF-1α/PKM2 positive feedback in vivo and in vitro." (PMID 34168560, 2021). "An animal study with RUPP rats showed that inhibition of HIF-1α using siRNA reversed the high blood pressure, renal damage, proteinuria, and elevated serum sFlt-1 level." (PMID 34681861, 2021). "On IHC, HIF1α-positive VSMCs were increased in number in two hypertension models, Ang II-infused mice and HS-diet rats, as compared with their control groups." (PMID 32283543, 2020). "Administration of superoxide dismutase mimetic resulted in inhibition of HIF-1α protein, catecholamines, and chronic intermittent hypoxia-induced hypertension in a mice model." (PMID 33013447, 2020). "To our knowledge, we are the first to study gene-environment interactions between the selected VHL and HIF1A SNPs and smoking, hypertension, BMI and alcohol consumption." (PMID 31924838, 2020). "This study demonstrated that inhibition of HIF1α signaling in VSMCs by genetic disruption in mice attenuated Ang II-induced hypertension and vascular remodeling." (PMID 31320613, 2019). "In another model of hypertension, renal neurogenic hypertension, induced by intrarenal injection of phenol, was shown to renal increase HIF-1α expression." (PMID 28701959, 2017). "In this regard, it should be mentioned that a functional cross-talk exists between hypertension and hypoxia, as hypoxic conditions which follow hypertension trigger HIF-1α expression and function." (PMID 23950890, 2013). "Furthermore, the local hypoxic environment induced by hypertension activates the HIF-1α signaling pathway, promoting the establishment of the liver pre-metastatic microenvironment." (PMID 41164182, 2025). "Indeed, IH-dependent HIF-1α activity has been proposed to hyperactivate the central and peripheral nervous system leading to hypertension." (PMID 40722943, 2025). "In addition to the central and peripheral nervous system, IH induces HIF-1α in heart and aortic tissue, which leads to oxidative stress, vascular smooth muscle cell migration, vascular remodeling, and systemic hypertension." (PMID 40722943, 2025). "Second, while we investigated the role of the Hippo–YAP pathway in hypoxia-exposed cells, further validation of whether HIF-1α exacerbates CIH-induced hypertension through the Hippo–YAP pathway in vivo is necessary." (PMID 39732653, 2024). "Therefore, this study explored the potential of the HIF-1α/Hippo-YAP pathway in the progression of SAS-related hypertension." (PMID 39732653, 2024). "Our findings suggest that targeting HIF-1α could be a promising therapeutic strategy for managing CIH-related hypertension in SAS patients." (PMID 39732653, 2024). "Furthermore, we investigated the influence of HIF-1α on oxidative stress and inflammation, which are critical components in the development of hypertension in SAS." (PMID 39732653, 2024). "However, the specific role and possible mechanism of HIF‐1α in the SAS in patients with hypertension are obscure." (PMID 39732653, 2024). "This study investigated the HIF-1α/Hippo-YAP pathway in SAS-related hypertension." (PMID 39732653, 2024). "miR-126a-3p targets HIF-1α and alleviates obstructive sleep apnea syndrome with hypertension." (PMID 36671757, 2022). "miR-199a-5p may relieve OSAS-related hypertension by targeting HIF-1α and be a novel potential therapeutic target." (PMID 35935584, 2022). "They concluded that exercise intervention underhypoxia may act as an alternative therapeutic strategy for hypertension patients,probably through the elevation of NOx and HIF-1α production." (PMID 39077598, 2022). "miR-199a-5p may relieve OSAS with hypertension by targeting HIF-1α and be a novel potential therapeutic target." (PMID 35935584, 2022). "Therefore, our results suggested that hypertension induces HIF-1α production, resulting in LDH-A production during Mtb infection." (PMID 34572127, 2021).
Hypertension (continued). "Further, HIF-1α mRNA levels have been shown to be regulated in an oxygen-independent manner by neurohumoral activators such as NE, commonly elevated in hypertension." (PMID 34912235, 2021). "Moreover, our previous study also found that QYYY improved the early renal damage of hypertension by inhibiting inflammatory reaction and reducing the expression of HIF-1α, some inflammatory factors and fibrosis indexes." (PMID 34168560, 2021). "Moreover, increased HIF-1α is associated with hypertrophy in the hearts and cultured neonatal rat cardiac myocytes, which is consistent with the role of HIF-1α in the heart for hypertension-induced hypertrophic cardiac remodeling via mitochondrial suppression." (PMID 34912235, 2021). "HIF-1α increases NADPH oxidase 2 (NOX2) mRNA expression, resulting in elevated reactive oxygen species (ROS) abundance, one of the risk factors contributing to the development of hypertension." (PMID 33669062, 2021). "The aim of study is designed to explore the mechanistic link between exaggerated sympathetic drive, miRNA/HIF-1α signaling and cardiac mitochondrial abnormalities and associated development of pathological cardiac remodeling in a rat model of neurogenic hypertension (NG-HTN)." (PMID 34912235, 2021). "In addition, interactions between VHL and HIF1A SNPs and smoking, hypertension, body mass index (BMI) and alcohol consumption were studied." (PMID 31924838, 2020). "In addition to hypoxia, RUPP animals also exhibited hypertension, proteinuria, and elevated levels of HIF-1α in the placenta on GD188,27." (PMID 30679723, 2019). "Interestingly, pretreatment with cobalt chloride, known HIF-1α activator, attenuated the development of hypertension and renal vasoconstriction." (PMID 28701959, 2017). "In addition, hypoxia can provoke hypertension through diverse mechanisms mediated by HIF-1α and leading to increased levels of catecholamines." (PMID 23950890, 2013). "Collectively, the present study provides novel data into the potential role played by GPER in hypertensive disease on the basis of its involvement in myocardial inotropism and lusitropism as well as the expression of the apoptotic HIF-1α and fibrotic CTGF factors." (PMID 23950890, 2013). "Therefore, MMP9, HIF1A, and BCL2 are closely linked to the onset and progression of hypertension, and catechin components may deliver their anti-hypertensive benefits through interactions with these target proteins." (PMID 39272451, 2024). "Pathologically, hypertension is characterized by arterial calcification, and one paper reported that capsaicin alleviates arterial calcification by upregulating Sirt6-mediated deacetylation of HIF1α, highlighting a potential therapeutic method for treating arterial calcification, even hypertension." (PMID 37497437, 2023). "As a transcriptional target gene of HIF1α, eNOS is increased in aorta tissue, and p-eNOS is enhanced after FG-4592 treatment in mice, indicating that HIF1α-regulated eNOS/p-eNOS may mediate FG-4592 effect against Ang II–induced hypertension." (PMID 34403364, 2021). "Therefore, we speculated that HIF-1α/PKM2 positive feedback is the key pathway of metabolic reprogramming of renal cell in hypertension." (PMID 34168560, 2021). "Moreover, CCL7 blockade attenuated Ang II-induced hypertension and vascular remodeling in vivo, indicating that HIF1α or CCL7 blockade may be a potential means for treating vascular remodeling disease." (PMID 31320613, 2019). "CG, GCG, ECG, and EGCG were identified as key catechin components for combating hypertension, with MMP9, HIF1A, and BCL2 as potential critical therapeutic targets." (PMID 39272451, 2024). "HIF-1α has been shown to regulate hypertension in mice; HIF-1α+/− mice show a significant decrease in hypertension induced by chronic-intermittent hypoxia compared to wild-type mice." (PMID 37092014, 2023).
Hypertension (continued). "The pathway enrichment analysis revealed the roles of the HIF-1-α transcription; endothelin; GPCR-binding ligand; and signaling pathways of EGF, PIk3, Arf6, S1P1, and PGDF in hypertension." (PMID 35205232, 2022). "ANO6, CXCR4, and HIF1A were significant also after adjustment for baseline variables showing an imbalance between STEMI and NSTEMI groups (age, hypercholesterolemia, hypertension, aspirin and statin use, time-to-presentation, admission cTnI)." (PMID 32457432, 2020). "Following the onset of hypertension (SHR bladder), markers such as HIF-1α, AT1, detrusor collagen, NGF, and TGF-β1/SMAD2/3 are upregulated, leading to increased fibrosis, reduced contractility, and decreased bladder capacity, while VEGF, MAS receptor (MASr), and antioxidants are decreased." (PMID 42162196, 2026). "HIF‐1α has been shown to be highly expressed in patients with SAS and hypertension." (PMID 39732653, 2024). "Using Western blotting protein expression of HIF-1α was found to be increased under high salt diet and in DOCA/salt hypertension and to be decreased in hypertension induced by nitric oxide synthase inhibition in combination with high salt diet." (PMID 37435301, 2023). "As hypertension generally raises TNF-α, IL-1β, IL-6, HIF-1α, TGF-β, and VEGF mRNA expression and/or protein levels, the results obtained in the studied model may provide a positive prognostic factor for such activity in vivo." (PMID 33652665, 2021). "Since it is known that hypertension generally raises TNF-α, IL-1β, IL-6, HIF-1α, TGF-β, and VEGF mRNA and/or protein levels, the results obtained in the study may provide a positive prognostic factor for such activity in vivo." (PMID 33652665, 2021). "Disruptions in the normal homeostatic balance between HIF-1α-dependent prooxidants and HIF-2α-dependent antioxidants in the CB induce oxidative stress and exacerbate SNS activity, one of the major determinants of hypertension." (PMID 32698380, 2020). "The original indication for the use of drugs was cardiovascular disease and/or hypertension but the severity in the HIF1α inhibitor group, and the presence of cardiovascular disease in men not on HIF1α inhibitors, was not recorded." (PMID 24464861, 2014). "P-PIC TLR3 KO mice did not develop hypertension and placental HIF-1α, NF-κBp50, miR-210, STAT6, and IL-4 levels were unchanged." (PMID 23844087, 2013). "In an angiotensin II (Ang II) hypertension model, FG-4592 abolished hypertensive responses; prevented vascular thickening, cardiac hypertrophy, and kidney injury; downregulated AGTR1 expression; and enhanced AGTR2, endothelial NO synthase (eNOS), and HIF1α protein levels in the aortas of mice." (PMID 34403364, 2021). "Therefore, drugs that selectively inhibit HIF-1α or upregulate HIF-2α in the CB, modulating the expression of NADPH oxidase 2 and Sod2 enzymes, could be potential targets for hypertension and OSA." (PMID 32698380, 2020). "Moreover, HIF-1α heterozygous-null mice (hif1a+/−) do not develop HTN when exposed to CIH, whereas hif2a+/− mice show hypertension and high norepinephrine plasma levels in normoxic conditions." (PMID 34447792, 2021). "While TLR3-activated pregnant mice developed hypertension, TLR3 knockout mice induced with poly:IC did not, nor did levels of miR-210, HIF-1α and NF- κB increase significantly." (PMID 27529341, 2016). "Intermittent hypoxia-induced increase in HIF-1α protein levels has been suggested as an adaptive response to OSA; however, negative effects of HIF-1α activation, such as hypertension and ischemic injury, have also been reported in animal models of OSA." (PMID 23923005, 2013).
diabetic nephropathy (68 papers, 2010 to 2026). "While an inverse association of the HIF-1α Pro582Ser polymorphism with diabetic nephropathy risk has been identified in genetic studies of patients and mouse models, its translation into clinical and therapeutic research is not yet available." (PMID 41357227, 2025). "HIF1A transcriptional regulatory networks were implicated in the pathogenesis and treatment of diabetic nephropathy." (PMID 40417738, 2025). "Deficiency of HIF1A has been shown to contribute to the development of diabetic nephropathy, whereas activation of HIF1A has been demonstrated to alleviate the condition." (PMID 40417738, 2025). "HIF-1α stabilization alleviated the metabolic reprogramming associated with renal dysfunction in an animal model of diabetic kidney disease." (PMID 36297636, 2022). "Recently, the downregulation of glomerular filtration rate (GFR) observed during diabetic nephropathy was associated with Hif-1α." (PMID 35046888, 2021). "On the other hand, deficiency of HIF1α in mice accelerated diabetic kidney disease progression and stabilization of HIF1α by PHD inhibitor attenuates ischemic kidney injury." (PMID 34867480, 2021). "As already shown, the HIF-1A Pro582Ser polymorphism is also protective for diabetic nephropathy (DN)." (PMID 31214621, 2019). "Diabetic nephropathy (DN) is characterized by renal hypoxia, increased oxidative stress, and defective nutrient deprivation signaling, which (acting in concert) are poised to cause both activation of HIF-1α and suppression of HIF-2α." (PMID 36142323, 2022). "On the other hand, the HIF-1A Pro582Ser polymorphism, which confers less sensitivity to the inhibitory effect of glucose during a hypoxic challenge, was shown to be protective toward development of advanced diabetic nephropathy and retinopathy." (PMID 34572324, 2021). "M-SYFSF exerts significant nephroprotective effects in diabetic kidney disease by targeting HIF-1α-mediated metabolic reprogramming." (PMID 41508092, 2026). "The role of HIF-1α in diabetic kidney disease has been increasingly recognized as both complex and context-dependent." (PMID 41508092, 2026). "This study demonstrates that M-SYFSY exerts significant nephroprotective effects in diabetic kidney disease through the modulation of HIF-1α-mediated metabolic reprogramming." (PMID 41508092, 2026). "Herein, we have demonstrated that PKM2 activation alleviates HIF-1α-mediated suppression of PGC-1α in diabetic kidney disease (DKD) models." (PMID 40713487, 2025). "Among these, CA9 exhibited the largest fold change within the transcriptional regulatory network of HIF1A, while PDK1 was most closely associated with diabetic nephropathy." (PMID 40417738, 2025). "PDK1, a downstream gene of HIF1A, is a critical mediator in diabetic nephropathy, with its downregulation promoting apoptosis in renal podocytes." (PMID 40417738, 2025). "HIF‐1α signalling can trigger pro‐fibrotic gene expression, rendering it a potential target in other diseases mediated by chronic fibrosis, including diabetic nephropathy and idiopathic lung fibrosis." (PMID 40824267, 2025). "It is postulated that the shift in the balance of HIF1A/HIF2A contributes to the progression of diabetic kidney disease (DKD) in humans." (PMID 41390888, 2025). "Tubular epithelial cell-derived extracellular vesicles have been reported to induce macrophage glycolysis by stabilizing HIF-1α in diabetic kidney disease." (PMID 40772233, 2025). "In diabetic nephropathy, insufficient HIF-1α activation was proposed as a factor of progression, and the efficiency of HIF-PHIs in renal anaemia treatment also points towards suboptimal activation." (PMID 37096392, 2023). "Ferroptosis, enhanced by excess ROS production, injured renal tubules, and promoted diabetic nephropathy via HIF-1α/HO-1 pathway in db/db mice." (PMID 37709486, 2023).